INS (insulin)
Diseases named in the same sentence as INS in open-access papers (continued):
Sharing a sentence is not in itself a finding about the gene and the disease.
Insulin resistance (continued). "In participants without prior COVID-19 status, FPG, insulin and total cholesterol associated with HOMA-IR-determined insulin resistance." (PMID 40273152, 2025). "This not only drives the sustained release of pro-inflammatory cytokines (such as IL-1β and TNF-α) but also disrupts insulin signaling through JNK/IRS-1 phosphorylation pathways, forming the pathological basis for chronic low-grade inflammation and insulin resistance." (PMID 40980312, 2025). "Lack of exercise has also been put forth as a driver of insulin resistance, but this does not explain how athletes become insulin resistant." (PMID 40421040, 2025). "Metformin did not reduce insulin resistance in type 1 diabetes, but lowered insulin dose versus placebo – a secondary outcome." (PMID 41285865, 2025). "Then homeostasis model assessment of insulin resistance (HOMA‐IR) was developed for clinical studies; however, it is susceptible to exogenous insulin therapy and is not suitable for patients with β‐cell incompetence." (PMID 40245241, 2025). "CAF feeding produced a classical metabolic syndrome–like profile with severe obesity, insulin resistance, dyslipidemia, and liver steatosis, whereas the FFD model led to moderate obesity with preserved insulin sensitivity but elevated blood pressure and hepatic cholesterol accumulation." (PMID 41305664, 2025). "Furthermore, vitamin D might decrease insulin resistance in peripheral insulin-target cells through the vitamin D receptor found in adipocytes, muscle, and hepatocytes while also promoting the expression of insulin receptors and improving insulin responsiveness for glucose transport." (PMID 40813680, 2025). "The Energy Model provides a framework for understanding that the important initial defect in insulin resistance is an increased metabolic demand for sugar rather than a decreased sensitivity to insulin." (PMID 40421040, 2025). "Therefore, Lac-Phe suppression of insulin-stimulated Akt signaling might at least partially be attributed to the direct or indirect activation of PTEN, especially considering the growing evidence of PTEN’s association with the development of insulin resistance and type 2 diabetes." (PMID 40862774, 2025). "In a palmitate-induced insulin resistance model involving HepG2 cells, celastrol upregulated the expression of miR-223, restored the levels of glucose transporter type 4/IRS1, and thereby enhanced insulin signaling." (PMID 40897829, 2025). "Adiponectin is a hormone related to insulin sensitivity, and inhibition of its expression with IGFBP-3 may further exacerbate insulin resistance." (PMID 40538800, 2025). "Chronic periodontitis-mediated insulin resistance and worsening of glycemic control are due to systemic inflammation and the release of pro-inflammatory cytokines such as TNF-α and IL-6 and other mediators by impairing insulin signaling pathways." (PMID 40136728, 2025). "TNF-α levels are inversely correlated with insulin sensitivity, while IL-6 and IL-1β inhibit insulin receptor substrate 1 (IRS-1); moreover, elevated levels of leptin in women with pregestational obesity contribute to insulin resistance." (PMID 41374008, 2025). "Insulin resistance—a precursor to type 2 diabetes—occurs when insulin is no longer effective at reducing blood glucose levels, triggering compensatory hyperinsulinemia and ultimately leading to the development of type 2 diabetes." (PMID 40937951, 2025). "Thus, insulin resistance seems to influence BGM in a manner that is modulated by the metabolic condition and/or level of insulin." (PMID 39185744, 2025). "Altogether, these results suggest that sEVPA-treated mice develop insulin resistance in hepatocytes without alterations in glucose homeostasis, pointing to a compensatory insulin secretion by the beta cells in vivo." (PMID 40387904, 2025). "Circulating FGF21 levels correlate with fasting insulin, insulin resistance, and BMI in people with T2D but not in healthy people." (PMID 40171198, 2025).
Insulin resistance (continued). "Research highlights that male students exhibiting insulin resistance typically present with elevated TC/HDL-C ratios compared to their counterparts without insulin resistance, establishing a positive correlation between the ratio and insulin sensitivity." (PMID 40144917, 2025). "The observed insulin resistance is likely due to epigenetic alterations, as it can be maintained for several generations even when insulin is not provided, and epigenetic modifiers can reverse it." (PMID 39471069, 2025). "Changes in insulin resistance markers were independent of body mass index variations and were predicted by baseline metabolic parameters including insulin, glucose, and lipid levels." (PMID 40863163, 2025). "Similarly, supplementation with inulin-type fructans in obese women significantly decreased BW, WC, BMI, homeostasis model assessment for insulin resistance (HOMA-IR), and fasting insulin, while improving satiety compared to the placebo group." (PMID 41007736, 2025). "Considering the influence of insulin resistance on the development of CAD, it appears that DPI may have a protective effect on CAD by affecting serum insulin levels." (PMID 41019185, 2025). "For example, oral trehalose treatment reverses plasma insulin levels and homeostasis model assessment-insulin resistance (HOMA-IR) in mice fed a high-fat diet (HFD), whereas intraperitoneal injection (i.p.)ameliorates insulin resistance in ob/ob mice." (PMID 40529415, 2025). "Insulin reduces FGF-23 so, in T1DM, low insulin leads to high levels while, in T2DM, insulin resistance may reduce them." (PMID 39941397, 2025). "At baseline, the mean fasting s-insulin and HOMA-IR levels indicated insulin resistance." (PMID 40939135, 2025). "Additionally, the fasting insulin level was increased in the 0.3 mg/kg·d PFOS group, indicating early insulin resistance." (PMID 41048434, 2025). "Insulin resistance in skeletal muscle is particularly important since it is normally responsible for more than 75% of all insulin-mediated glucose disposal." (PMID 40894926, 2025). "Consequently, exogenous NTs ameliorate insulin resistance in HepG2 cells by modulating the IRS-1/AKT/FOXO1 pathways and regulate glucose consumption, glycogen content, insulin signaling pathways, AMPK activity, oxidative stress, and inflammatory status." (PMID 38931156, 2024). "In addition, as assessed with fasting blood glucose and insulin levels, the SP group had overt glucose intolerance and elevated HOMA-IR, a key indicator of insulin resistance." (PMID 38561446, 2024). "In a 24-week study, participants consuming four cups of caffeinated coffee per day saw no significant change in insulin sensitivity, fasting blood glucose levels, or biological indicators of insulin resistance." (PMID 39201652, 2024). "Type 2 diabetes is a result of insulin resistance and obesity, which can be fully compensated for by β-cells in the absence of sufficient insulin sensitivity." (PMID 39104999, 2024). "Insulin resistance, defined as reduced insulin sensitivity and detected in approximately 40% of patients with NAFLD, arises from the reduced expression of insulin receptors, ineffective insulin-receptor bindings, or impairment in insulin signaling." (PMID 38542310, 2024). "This improves skeletal muscle mitochondrial mass reduces serum TG, TC, non-esterified fatty acid (NEFA), blood glucose, and insulin levels, and improves lipid metabolism, glucose tolerance, and insulin resistance in db/db mice." (PMID 38348222, 2024). "Compared to age-matched controls, insulin resistance in the brains of PD patients is independent of peripheral insulin resistance and manifests as severe abnormalities in brain insulin signal transduction." (PMID 39719978, 2024).
Insulin resistance (continued). "Compared with the 12L:12D photoperiod, the serum glucose (GLU), serum insulin (INS), serum triglyceride (TG) levels, and homeostasis model assessment of insulin resistance (HOMA-IR) of broilers significantly enhanced in the 18L:6D and 24L:0D photoperiods (p < 0.05)." (PMID 39457933, 2024). "While HOMA-IR is a more comprehensive index for assessing insulin resistance, its reliance on insulin serum levels—tests not routinely conducted in clinical practice—limits its use as a screening tool." (PMID 39765929, 2024). "Next, CWO were segregated on the basis of insulin sensitivity or resistance using HOmeostatic Model Assessment for Insulin Resistance (HOMA-IR) model which predicts pancreatic-cell function and insulin sensitivity for a given combination of fasting levels of plasma glucose and insulin." (PMID 38467728, 2024). "Additionally, SPs from seaweeds mitigated inflammation and insulin resistance, as evidenced by reduced TNF-α levels and serum insulin concentrations, particularly in obese animal models." (PMID 39728103, 2024). "As elevations in plasma glucagon concentrations are implicated with hepatic steatosis, independent of insulin resistance, these results suggest that reduced ICR is a consequence of intra-hepatic lipid accumulation rather than insulin resistance per se." (PMID 39138690, 2024). "Despite pathogenic pathways not being completely understood, many studies (not all) showed an increase in insulin sensitivity after parathyroid tumor removal (and some revealed an improvement in high blood pressure independently of insulin resistance." (PMID 38928056, 2024). "Moreover, TLR4 inhibition prevents insulin signaling dysfunction and improves behavioral and molecular impairments, highlighting the critical role of TLR4 in the development of insulin resistance in PD pathology." (PMID 39830652, 2024). "GK rats represent a non-obese model of type 2 DM and exhibit insulin resistance and an insulin secretory defect." (PMID 38399315, 2024). "Furthermore, a high-fat diet combined with sodium butyrate supplementation (5% w/w) reduced homeostasis model assessment-estimated insulin resistance (HOMA-IR), fasting blood glucose, and insulin levels." (PMID 38398822, 2024). "To assess whether LrB affected insulin resistance in the PCOS-IR rat model, we measured FBG and INS concentrations." (PMID 39456928, 2024). "Lastly, this study focused on hospitalized patients with coronary heart disease who were not routinely tested for insulin levels, and therefore, a comparison between the homeostatic model assessment for insulin resistance and the TyG index was not conducted." (PMID 39136595, 2024). "Both FLLE and FLRE treatment could reduce insulin resistance in TNF-α-induced adipocytes, which is consistent with a previous study in which ethanolic and methanolic extracts of Ficus deltoidei increased insulin-mediated glucose uptake." (PMID 38543073, 2024). "Additionally, we are contrasting the homeostatic model assessment for insulin resistance (HOMA-IR) values with urine MMP-7 values to provide a predictive value for glycemic excursion and insulin sensitivity." (PMID 39246865, 2024). "Also, the Sphingomonas group had similar fasting insulin and glucose levels to the PGR group, as well as same insulin resistance as indicated by the HOMA-IR index." (PMID 39872217, 2024). "Our investigation revealed elevated insulin levels in both female OVX/HFHSD mice and diabetic human subjects, concomitant with decreased INSR expression in both groups, indicating a reciprocal relationship between insulin resistance and INSR levels." (PMID 39337631, 2024). "The homeostasis model assessment insulin resistance (HOMA-IR) index, as a marker of insulin resistance, was 3.9 (normal range <1.6), and the HOMA-β index, as a marker for insulin-secreting capacity, was 13 (normal range, 40-60), indicating insulin resistance and impaired insulin secretion." (PMID 38745825, 2024).
Insulin resistance (continued). "The nascent phenotype is characterised by high beta cell function and no insulin resistance (high insulin sensitivity), similar to the MOD cluster which explains the patients’ flow to the cluster." (PMID 39217248, 2024). "We further divided obese individuals into low, intermediate, and high LEPROT levels and grouped them into 3 HOMA-IR categories assessing normal insulin sensitivity (HOMA-IR < 1.9), intermediate insulin resistance (1.9 < HOMA-IR < 2.9), or insulin resistance status (HOMA-IR > 2.9)." (PMID 38716728, 2024). "Control C57BL6/J mice lacking functional Nnt gene housed on standard, low-fat diet are still significantly more glucose-tolerant and insulin sensitive from their high-fat diet-fed counterparts, which validates the use of C57BL/6J strain in the studies on high-fat diet-induced insulin resistance." (PMID 39178212, 2024). "It results when the pancreas fails to produce insulin (type 1) or when the body cannot effectively use insulin, known as insulin resistance (type 2)." (PMID 39867016, 2024). "The data presented here as well as those from others suggest that in individuals with obesity, resveratrol treatment can be sufficient in ameliorating insulin resistance independent of improvement in insulin signal transduction." (PMID 38324260, 2024). "Third, the study did not investigate the impact of insulin resistance because insulin levels were not assessed during routine health checkups." (PMID 39259121, 2024). "We evaluated the effect of APPxhQC transgenes and T2D induction on fasting plasma insulin levels (FPI), fasting plasma glucose levels (FPG), homeostatic model assessment for insulin resistance (HOMA-IR) and homeostasis model assessment of beta-cell function (HOMA-β)." (PMID 38763496, 2024). "The greater insulin resistance is in line with previous literature, although historically, this has relied on isolated fasting glucose and insulin concentrations rather than robustly exploring glycaemic control." (PMID 38923603, 2024). "Insulin resistance was not due to an impairment of fetal or offspring growth, nor to an alteration in adipose sensitivity to insulin." (PMID 38478198, 2024). "On the other hand, GDM occurs when maternal β-cell insulin secretion fails to compensate for the gradually increasing insulin resistance during pregnancy, and typically resolves after delivery." (PMID 38302966, 2024). "Metformin-treated individuals (G1) showed significant differences in insulin levels and homeostatic model assessment of insulin resistance (HOMA-IR) when compared to the non-metformin-treated (G3) group." (PMID 38370354, 2024). "We show that participants with rare heterozygous deleterious FGFR1 SNVs demonstrate higher insulin/C-peptide response to glucose and higher insulin resistance compared to noncarriers." (PMID 38957656, 2024). "Results from a small cross-sectional study found individuals who maintained a long-term SV had lower insulin concentrations and insulin resistance (HOMA-IR) when compared to non-vegetarians." (PMID 39462384, 2024). "Similarly, the expression of c-miR-126 has also been shown to be altered with exercise and concomitantly a potential biomarker for type-2 diabetes due to its interference with insulin signaling by targeting IRS1 and IRS2, resulting in insulin resistance." (PMID 38903909, 2024). "Since ZDF rats have severe insulin resistance, the sustained levels of hepatic cAMP found in ZDF rats may result from resistance to this acute action of insulin." (PMID 38265288, 2024). "Unlike the homeostasis-model-assessment-estimated insulin resistance index, its calculation does not need to estimate plasma insulin levels." (PMID 39685728, 2024). "We posit that restoring D-Chiro-Ins levels can be beneficial in ameliorating insulin resistance in non-ovarian tissues, thereby reducing the insulin stimulation upon TCs and, hence, the consequent insulin-dependent enhancement of androgenesis." (PMID 39056753, 2024).
Insulin resistance (continued). "Insulin resistance limits the transportation of GLUT4 transporter proteins to the cell membrane due to the lack of insulin stimulation." (PMID 39771098, 2024). "Furthermore, two separate RCTs reported both vegans and LOVs interventions reduce insulin resistance (HOMA-IR) and insulin levels when compared to an omnivorous intervention after 16 weeks and 24 weeks, respectively." (PMID 39462384, 2024). "In turn, in non-obese and moderately obese patients with insulin resistance, irisin release from muscles is reduced as a result of muscle resistance to insulin." (PMID 38474169, 2024). "Insulin has been reported to cross the dermal-epidermal junction and affect keratin-forming cells, and the downstream PI3-K/Akt/mTOR signaling cascade is a common and important signaling pathway in obesity, insulin resistance and psoriasis." (PMID 38917217, 2024). "Homeostasis model assessment of insulin resistance (HOMA-IR) was calculated from FBG and insulin." (PMID 37930396, 2024). "The hepatic insulin resistance (hepatic-IR) index coming from the measurement of plasma glucose and insulin concentrations during an oral glucose tolerance test (OGTT) is presented for quantitation of hepatic insulin sensitivity." (PMID 39175570, 2024). "Considering the low glucose uptake and insulin resistance of the PGR piglets, adiponectin may decrease the level of circulating glucose, which may help to increase insulin sensitivity." (PMID 39872217, 2024). "In addition, although C-peptide is a robust equimolar insulin secretion marker and indicator of beta cell function in response to an MMTT, other factors such as insulin resistance and renal impairment can affect serum C-peptide concentration." (PMID 38662134, 2024). "Notably, disturbances in insulin signaling through the inhibition of the insulin receptor substrate protein, phosphoinositide-3-kinase, and protein kinase B (AKT) lead to insulin resistance even when suffering from diseases like cancer." (PMID 39674630, 2024). "The gene expression of insulin function-related molecules in the liver was significantly lower in the STZ-pregnant group than in the CB-pregnant group, which contributed to enhanced insulin resistance." (PMID 38626157, 2024). "In insulin resistance, not all signals are read correctly and thus the body increases the production both of insulin in the pancreas and glucose in the liver." (PMID 38792339, 2024). "In patients with T2DM, the blockade of IL-1 receptor signaling improves glycemic control and the ability to secrete insulin, but not insulin resistance itself, as evaluated by insulin-regulated gene expression in skeletal muscle and serum adiponectin levels." (PMID 38256005, 2024). "This is analogous to insulin resistance in type 2 diabetes, where high insulin levels do not produce the expected metabolic effects." (PMID 39594988, 2024). "Surprisingly, BMAT retained its responsiveness to insulin and did not display a pro-inflammatory phenotype or insulin resistance, which contrasts with the behavior observed in peripheral adipose tissue." (PMID 38727260, 2024). "T1DM is defined by a severe or total lack of insulin, while T2DM is identified by insulin resistance and inadequate compensatory insulin production." (PMID 39715797, 2024). "An animal study on pregnant mice found that TCS-treated mice had increased fasting blood glucose (FBG), insulin (INS), and homeostasis model assessment 2 of insulin resistance (HOMA2-IR) levels, and decreased homeostasis model assessment 2 of β cell function (HOMA2-β)." (PMID 39596180, 2024). "A Hertfordshire cohort study in the British population found negative correlations between DTAC and fasting insulin, insulin resistance, and glucose tolerance using four DTAC measurement methods." (PMID 38553719, 2024).